RAB25 (RAB25, member RAS oncogene family)
Diseases named in the same sentence as RAB25 in open-access papers (continued):
Sharing a sentence is not in itself a finding about the gene and the disease.
ovarian carcinoma (continued). "Conversely, Rab25 expression correlates with decreased survival and increased aggressiveness of ovarian cancer, and enhanced invasive migration of ovarian cancer cells in vitro." (PMID 22197222, 2012). "Finally, the clinical significance of this upregulation was investigated by examining the expression of Rab25 and Rab35, two G-protein-related molecules in an ovarian cancer tissue microarray (TMA)." (PMID 19623182, 2009). "Endogenous Rab25 is expressed in BT20 cells, albeit at a lower level than in the A2780-Rab25 line, in which overexpression levels reflect those found in aggressive ovarian cancers." (PMID 37232246, 2023). "(C) Bioinformatic analysis of DNA promoter methylation (Methylation27K) of Rab25 and its expression (RNAseq; RPPA) in ovarian cancer (OV) using UCSC Xena (TCGA Pan-Cancer study)." (PMID 35708998, 2022). "At least in ovarian cancer, RAB25 regulates HIF-1α activity in an oxygen-independent manner, suggesting that RAB25 lies upstream to hypoxia-based induction of glycogen metabolism." (PMID 33224887, 2020). "Rab25 ectopic overexpression was found to increase development of xenograft derived from breast cancer cells (MCF7) and ovarian cancer cells (A2780, HEY)." (PMID 28969096, 2017). "Conversely, ectopic overexpression of Rab25 was found to induce in vitro cell growth of breast cancer cells (MCF7) and ovarian cancer cells (A2780, DOV13, HEY, OCC1)." (PMID 28969096, 2017). "Knockdown of Rab25 by siRNA transfection decreased cisplatin resistant of NSCLC cells and ovarian cancer cells." (PMID 28969096, 2017). "Similar effects on cisplatin resistance in vitro and intraperitoneal tumourigenesis in vivo were obtained after HIF1b knockdown in the ovarian cancer cell line SKOV3, which expresses endogenous Rab25 and HIF-1α at atmospheric oxygen concentrations." (PMID 26967059, 2016). "For instance, the ovarian cancer oncogenes CCNE1 and RAB25 show significant methylation and expression correlation for both amplified and deleted copy number aberrations." (PMID 22174824, 2011). "Taken together, the dramatic up-regulation of RAB25 and down-regulation of TUSC3 in RIα cells appears to faithfully mimic the activity profiles of proven markers of ovarian cancer clinical progression." (PMID 18822129, 2008). "Rab25-mediated EGFR recycling and elevated levels of nuclear EGFR correlate with poor prognosis in ovarian cancer, and our data which suggest that Rab25 may be connected with nuclear envelope-associated endosomes warrants further investigation." (PMID 35708998, 2022). "A2780 ovarian cancer cells show abundant Rab11a/b expression while the more restricted family member Rab25 is not expressed." (PMID 35708998, 2022). "A significant positive correlation between Rab25 and AR expression was also found in ovarian cancer specimens, although there is no direct evidence indicating that androgens regulate the expression/activity of Rab25." (PMID 30791431, 2019). "Ectopic overexpression of Rab25 induced phospho-ERK1/2, which is one of the downstream signaling molecules of Src, and may lead to cisplatin resistance of ovarian cancer." (PMID 28969096, 2017). "Rab25, an oncogene of ovarian cancer, shows a negative correlation between promoter methylation and mRNA expression." (PMID 28969096, 2017). "Moreover, Rab25 suppressed apoptotic cell death by reducing the expression of pro-apoptotic molecules, BAX and BAK, in ovarian cancer." (PMID 28969096, 2017). "Rab25 was initially identified in a series of ovarian cancers that did not respond to chemotherapy and subsequently shown to prevent apoptosis and anoikis induced by taxol-based chemotherapy." (PMID 26967059, 2016). "Rab25 and CLIC3 levels correlated with one another in both pancreatic and ovarian carcinoma." (PMID 22197222, 2012). "Furthermore, it has been suggested that Rab25, a small GTPase of the Ras family, might upregulate ADAMTS5 expression in ovarian cancer cells." (PMID 40164572, 2025).
ovarian carcinoma (continued). "In ovarian cancer, the overexpression of the small GTPase Rab25 promotes the internalisation of fibronectin-occupied α5β1 integrin to sustain invasive migration; therefore, we measured ECM internalisation in the highly invasive ovarian carcinoma cell line A2780, overexpressing Rab25 (A2780-Rab25)." (PMID 39666682, 2024). "RAB25 is highly expressed in epithelial ovarian cancers but not in stromal tumors." (PMID 24403269, 2013). "In addition to RAB25 amplification, rearrangements and increased expression of the S100A4 gene have been correlated with advanced disease stages and poor survival in other malignancies, such as ovarian osteosarcoma metastasis and ovarian carcinoma." (PMID 23825676, 2013).
breast carcinoma (36 papers, 2010 to 2026). "We were interested in understanding if RAB25 loss is associated explicitly with H-RAS mutations or even other oncogenes commonly mutated in breast cancer." (PMID 38803515, 2024). "The loss of RAB25 expression—RAS superfamily of GTPase characteristic of numerous breast cancers—corresponds with H-RAS point mutations, particularly in triple-negative breast cancers (TNBC), a subtype associated with a poor prognosis." (PMID 38803515, 2024). "We have previously shown the importance of loss of RAB25 expression in breast cancer, and RAB25 serves as a tumor suppressor in TNBC." (PMID 38803515, 2024). "To understand the significance of the loss of RAB25 expression in spindle cell breast cancer, we expanded our study to look at the expression of RAB25 in clinical samples." (PMID 38803515, 2024). "Several studies on ovarian cancer, renal cell carcinoma, luminal B breast cancer and advanced non-small lung cancer have described RAB25 as an oncogene, associated with metastasis and a poor prognosis." (PMID 30445998, 2018). "It would be intriguing to associate a vesicular trafficking protein like Rab25 with stem cell like properties of breast cancer cells." (PMID 27259233, 2016). "Research has identified that loss of Rab25 expression occurs through a mutation in locus 1q22-23 of human breast cancer tissues." (PMID 25815277, 2015). "In hormone receptor-positive breast cancer, RAB25 expression is a poor prognosis factor, whereas the breast cancer subtype with the worst prognosis, triple negative for hormonal receptors presents loss of RAB25 expression." (PMID 24403269, 2013). "A growing number of Rab proteins such as rab5, rab11, rab21, rab25, and rab27B have been shown to be associated with tumor growth/behavior and prognosis of breast cancer patients." (PMID 22920728, 2012). "Studies on human breast cancer tissues have shown that loss of Rab25 expression occurs through a mutation in locus 1q22-23." (PMID 21143914, 2010). "Notably, FOXA1 and RAB25 are strongly implicated in breast cancer biology, and FOXA1 has been directly linked to the aryl hydrocarbon receptor (AHR), the main regulator of CYP1A1." (PMID 41901204, 2026). "Loss of Rab25 is also common in basal subtypes of breast cancer." (PMID 32842549, 2020). "Finally, we found a causal association of Rab25 with cellular lineage in the context of breast cancer that needs further evaluation." (PMID 27259233, 2016). "Conversely, loss of RAB25 is associated with a poor prognosis in ER-negative breast cancer, and RAB25 behaves as a tumor suppressor in breast cancer cell lines by decreasing cell migration/invasion and affecting pathways including the VEGF-A/VEGFR-1 autocrine loop." (PMID 24216980, 2013). "Considering that Rab25 is an epithelial specific GTPase and is part of the 1q amplicon that is common across breast cancer subtypes, we hypothesized that Rab25 expression and function would be positively associated with progression of breast cancers with epithelial features." (PMID 27259233, 2016). "CRACR2A was also required to support migration of MDA-MB-231 breast cancer cells (which lack Rab25 expression, but express high levels of CRACR2A) in the 3D CDM." (PMID 37232246, 2023). "In a different cell type, BT20 breast cancer cells, knockdown of Rab4a, Rab4b, Rab11a, Rab11b or Rab25 significantly decreased motility, as did knockdown of CLINT1 or SH3BP5L." (PMID 37232246, 2023). "A recent study extended the relevance of this finding to breast cancer: The authors demonstrated that the expression of let-7d and Rab25 were inversely correlated in a study on 110 breast cancer samples and adjacent tissues." (PMID 34298978, 2021).
breast carcinoma (continued). "Both Rab25 and the mesenchymal marker snail were upregulated in breast cancer tissue, and were correlated, leading the authors to suggest that let-7d regulated EMT in breast cancer by targeting Rab25." (PMID 34298978, 2021). "For example, Rab25 expression in breast cancer tissues is 67% higher than that in normal breast epithelial cells." (PMID 30755162, 2019). "As a final filter for RFP optimization, confocal fluorescence microscopy was used to evaluate RFP cellular penetration in MCF7 breast cancer cells, which express RAB25." (PMID 28939823, 2017). "In contrast, RFP14 treatment augments these phenotypes in breast cancer cells in which RAB25 is tumor suppressive." (PMID 28939823, 2017). "Several optimized cell permeable stapled peptides disrupt RAB25:FIP complex formation in vitro and in situ, and oppose the context-specific phenotypes associated with RAB25 function in ovarian and breast cancer cell lines." (PMID 28939823, 2017). "It is already known that Rab25, a Rab11 GTPase whose expression is largely restricted to epithelia, is often lost in breast cancer, and deletion of Rab25 accelerates tumorigenesis in a mouse model of colon cancer." (PMID 28062852, 2017). "This dichotomy exists despite the presence of the 1q amplicon that hosts Rab25 across breast cancer subtypes and is likely due to differential methylation of the Rab25 promoter." (PMID 27259233, 2016). "In this study we have illustrated a context dependent role for Rab25, where it acts as an oncogene in luminal B breast cancer and as a tumor suppressor in claudin-low tumors." (PMID 27259233, 2016). "Here we have identified the Rab25 vesicular trafficking protein as a biomarker of disease progression in the luminal B subtype of breast cancer." (PMID 27259233, 2016). "To explore the context dependent role of Rab25 in breast cancer subtypes, we created stable lines with exogenously manipulated levels of Rab25 in a luminal B background (such as MCF7, T47D) as well as in basal (MCF10A) or claudin-low background (MDA231)." (PMID 27259233, 2016). "Herein we demonstrate that Rab25, a key GTPase, mostly decorating the apical recycling endosome, is a dichotomous variable in breast cancer cell lines with higher mRNA and protein expression in Estrogen Receptor positive (ER+ve) lines." (PMID 27259233, 2016). "Since upregulation of mitogenic signals such as Mitogen Activated Protein Kinase (MAPK or ERK1/2) is a common feature of aggressive breast cancers we tested if Rab25 levels alter the activity of ERK kinase." (PMID 27259233, 2016). "Overall, this study substantiates a striking context dependent role of Rab25 in breast cancer where Rab25 is amplified and enhances aggressiveness in luminal B cancers while in claudin-low tumors, Rab25 is lost indicating possible anti-tumor functions." (PMID 27259233, 2016). "As expected, the best prognosis for luminal B breast cancer subtype occurred in patients with both low Rab25 and low RCP levels." (PMID 27259233, 2016). "This was surprising given that the 1q amplicon that contains Rab25 is prevalent across all breast cancer subtypes." (PMID 27259233, 2016). "Next, to confirm if Rab25 mediated its oncogenic effects through RCP in luminal B breast cancer, we altered levels of Rab25 or RCP and interrogated the cells for expression as well as functional assays." (PMID 27259233, 2016). "Of these, expression of IFI16 and ANKD1 were particularly strongly associated with RAB25 and ESRP1 levels in primary breast cancer." (PMID 26646320, 2016). "Overall, in this study we discovered that Rab25 is a context dependent oncogene with a potential role in breast cancer cell plasticity (which needs further in depth analysis in the future)." (PMID 27259233, 2016). "Functionally, elevated levels of Rab25 drive major hallmarks of cancer including indefinite growth and metastasis but in case of luminal B breast cancer only." (PMID 27259233, 2016).
breast carcinoma (continued). "Taken together our data shows that only in luminal B breast cancers, increased levels of Rab25 facilitate cell survival." (PMID 27259233, 2016). "RAB25 induces apoptosis in TN breast cancer, and reduced expression of RAB25 is involved in PB resistance." (PMID 26646320, 2016). "Oncogenic gene amplification and overexpression of Rab25 have been detected in ovarian and breast cancer, whereas they function as a tumor suppressor in colon cancer." (PMID 24658031, 2014). "Rab25, for instance, has been demonstrated to inhibit apoptosis as well as promote the proliferation and aggressiveness of ovarian and breast cancer." (PMID 25580113, 2014). "Nevertheless, in the past 2 years, it has become clear that Rab25 overexpression in breast cancer is likely less common and that indeed, at least in oestrogen receptor-deficient cancers, expression is actually decreased significantly." (PMID 21063400, 2011). "Given the results in both ovarian and breast cancer studies, it is likely that Rab25 influences the trafficking and recycling of a number of key regulators of polarity and signalling involved in transformation." (PMID 21063400, 2011). "Rab25 has been shown to decrease apoptosis, as well as to increase both the proliferation and aggressiveness of ovarian and breast cancer." (PMID 21143914, 2010). "Loss of RAB25 in breast cancer is not noted in CBioPortal data, but our previous studies indicate that it can occur with significant frequency in triple-negative breast cancers." (PMID 38803515, 2024). "Elevated levels of RAB25 are reported in the ER and PR positive subtypes of breast cancer and in the ER and PR negative breast cancer subtypes; we see the loss of RAB25 leading to activation of the RAS signaling pathway." (PMID 38803515, 2024). "Our previous results have confirmed RAB25 as a tumor suppressor in breast cancer." (PMID 38803515, 2024). "Furthermore, miR-577 inhibited the proliferation and EMT process via suppressing Rab25 expression in breast cancer." (PMID 34821374, 2022). "In addition, overexpressed RAB25 in breast cancer cells decreases the apoptosis and increases the proliferation and aggressiveness in vivo." (PMID 36360219, 2022). "The Rab25 targeting peptide, RFP14, preferentially binds to Rab25 over Rab11a and inhibits cell proliferation and migration in the breast cancer cell lines in which Rab25 is oncogenic, but augments these phenotypes in the cell lines in which it is tumour-suppressive." (PMID 32842549, 2020). "The induction effect was further increased by co-treatment of DNA methylation inhibitor and histone deacetylases inhibitor in breast cancer cell and lung squamous adenocarcinoma cells, proofing the elevation of Rab25 level by promoter demethylation and acetylation." (PMID 28969096, 2017). "The list of effectors of Rab25 are increasing and while Rab11Fip1 or RCP was found to be a functional accomplice of Rab25 in luminal B cancers and is key for better stratification of luminal B patients, we are yet to understand the dynamics of Rab25-RCP in the other breast cancer subtypes." (PMID 27259233, 2016). "In vitro, Rab25 increased proliferation, sustained indefinite growth and promoted motility in luminal B breast cancer cell lines while exerting the opposite effect on basal-like breast cancer cell lines." (PMID 27259233, 2016). "Therefore, the ambiguous role of Rab25 in cancer initiation, progression and prognosis, including its role in breast cancer progression is confusing, conflicting, and poorly understood." (PMID 27259233, 2016). "Loss of RAB25 expression has been associated with tumor initiation and poor prognosis in colon, esophageal and estrogen receptor (ER)-negative breast cancer." (PMID 24403269, 2013).